RN7SL307P (RNA, 7SL, cytoplasmic 307, pseudogene)
Gene: Miscellaneous RNA gene on chromosome 15 (49,198,900 to 49,199,194, reverse strand). Ensembl gene ENSG00000243338.
Homologues: Orthologues: chimpanzee Metazoa_SRP (99% identical), macaque Metazoa_SRP (94% identical). Paralogues in human: RN7SL1 (80% identical), RN7SL2 (80% identical), RN7SL3 (79% identical), RN7SL478P (76% identical), RN7SL126P (76% identical), RN7SL630P (76% identical), RN7SL650P (76% identical), RN7SL14P (75% identical), RN7SL18P (75% identical), RN7SL444P (75% identical), RN7SL480P (75% identical), RN7SL556P (75% identical), and 701 more.